KL (klotho)
Diseases named in the same sentence as KL in open-access papers (continued):
Sharing a sentence is not in itself a finding about the gene and the disease.
hyperphosphatemia (continued). "Current literature supports such a thesis, and has indicated that the development and progression of CKD is significantly associated with a dysregulated FGF23-Klotho pathway, resulting in hyperphosphatemia and endothelial dysfunction." (PMID 32982966, 2020). "The overexpression of Klotho resulted in longer life span, whereas its suppression in deficiency mice led to aging-like phenotypes mediated by hyperphosphatemia." (PMID 33291777, 2020). "In a previous work, we addressed the influence of KL gene variants in recalcitrant hyperphosphatemia in two groups of adult age and gender-matched dialysis patients with high or normal serum phosphate levels despite optimization of treatment." (PMID 31013726, 2019). "This suggests that hyperphosphatemia and α-klotho deficiency potentially are drivers of renal injury in the mouse models of CKD that we studied." (PMID 31575945, 2019). "This phenotype is also observed in 2- and 4-week ADE-treated mice and in a mouse model with partial deletion of klotho in distal tubular segments (Ksp-KL−/−), which is associated with hyperphosphataemia and elevated FGF23." (PMID 30393837, 2019). "First, a homozygous missense mutation leading to an attenuated production of Klotho translated in hyperphosphatemia, hypercalcemia, and both vascular and ectopic calcification in the brain and the Achilles tendon." (PMID 30713844, 2018). "Serum phosphate levels inversely correlate with the lifespan of diverse species and hyperphosphatemia has been linked with premature aging phenotype in Klotho deficient mice and in FGF23 KO mice." (PMID 30271655, 2018). "Klotho mutant mice develop early hyperphosphatemia and hypercalcemia with a high risk of ectopic calcifications and accelerated osteoporosis due to a reduction in the number of both osteoclasts and osteoblasts." (PMID 28912623, 2017). "Mutation of the Klotho gene (KL) leads to numerous premature-aging phenotypes, including soft tissue calcification, emphysema, sex gland dysplasia, infertility, and hyperphosphatemia." (PMID 29179433, 2017). "High serum FGF23 levels are primarily associated with LVH, whereas low serum Klotho levels and hyperphosphatemia are associated with endothelial dysfunction, atherosclerosis and fibrosis." (PMID 27189482, 2016). "In mice, the deletion of Klotho gene causes a phenotype of premature human aging including vascular calcification, altered calcium/phosphate metabolism with hyperphosphataemia, and shortened lifespan." (PMID 22121479, 2012). "Reduction in soluble Klotho has been associated with renal disease, hyperphosphataemia, increased oxidative stress, endothelial dysfunction, and diffuse vascular calcification." (PMID 22121479, 2012). "On the other hand, defects or mutations in Fgf23 or Klotho resulted in hyperphosphatemia, premature aging, and the formation of ectopic calcifications." (PMID 22879941, 2012). "Klotho insufficiency causes hyperphosphatemia and other anomalies." (PMID 39272986, 2024). "Klotho-deficient mice carrying either hypomorphic or knockout (KO) alleles display a syndrome that manifests several phenotypic features of aging, including early lethality, hyperphosphatemia, renal disease, multisystem defects, and male infertility." (PMID 37759974, 2023). "Klotho deficiency in experimental mice models leads to a phenotype characterized by an altered calcium/phosphate metabolism with hyperphosphatemia, secondary hyperparathyroidism, vascular calcification, cardiac hypertrophy, premature aging, and a shortened lifespan." (PMID 36293076, 2022). "Disturbance of harmony among these factors, either solo or in alliance, may provoke phosphorus disproportion, and the inhibition of the FGF23 Klotho system can cause hyperphosphatemia with widespread tissue injury instigated by hyperphosphatemia." (PMID 36105908, 2022).
hyperphosphatemia (continued). "The present article reports, in a 67-year-old woman with hyperphosphatemia undergoing hemodialysis treatment, the identification of a novel heterozygous deletion variant in the KL gene (p.Ile348Phefs*28), possibly degraded by mRNA decay, that affects FGF23 signaling and leads to haploinsufficiency." (PMID 31013726, 2019). "Indeed, the phenotypes of FGF23 and α-klotho deficiency are very similar, with hyperphosphataemia and increased synthesis of 1,25(OH)2D3, and indicate the cooperative action of α-klotho and FGF23 in a common signalling pathway." (PMID 30393837, 2019). "We hypothesized that genetic variation in the KL gene might be associated with alterations in phosphate homeostasis resulting in hyperphosphatemia." (PMID 31013726, 2019). "Administration of NYT to klotho-deficient mice protects from atrophy and increases physical performance, which might be based on the protective effects against the pathologic actions of hyperphosphatemia." (PMID 38791164, 2024). "Notably, hyperphosphatemia has been shown to induce DNA damage in vascular smooth muscle cells, resulting in cellular senescence, which further contributes to the premature aging process observed with Klotho dysregulation or loss." (PMID 32982966, 2020). "These similarities lead to speculate that genetic variants in the human KL gene could result in a disruption of renal phosphate excretion, and therefore contribute to the resistant hyperphosphatemia observed in some CKD patients despite the optimization of therapeutic strategies." (PMID 31013726, 2019). "Low Klotho (often due to kidney disease) produces hyperphosphatemia, which injures cells (especially endothelial cells) and promotes aging." (PMID 41892298, 2026). "In humans, genetic deficiencies of klotho and of Fgf23 as well as the regulators of FGF23 production cause familial tumoral calcinosis, which is a rare genetic disease with hyperphosphatemia and ectopic calcifications." (PMID 40471241, 2025). "Accelerated osteoporosis, hyperphosphatemia, skin atrophy, and infertility of both sexes indicated that Klotho was crucial for survival." (PMID 39277686, 2024). "Klotho knockout mice develop hyperphosphatemia with subsequent severe vascular calcification, and therefore, they have been used as a model of this disorder." (PMID 38256228, 2024). "Klotho, an anti-aging protein expressed in the distal convoluted tubules, is reported to induce hyperphosphatemia as its inhibitory effect on the proximal tubule Na-coupled phosphate transporter is lost." (PMID 37112600, 2023). "Hyperphosphatemia, the fluctuations of calcium such as hyper and hypocalcemia, hyperparathyroidism, the reduction of alpha Klotho, and the increase in FGF-23 are the main determinants of AS in CKD." (PMID 37510208, 2023). "The biochemical hallmark of tumoral calcinosis, hyperphosphatemia, is caused by increased renal absorption of phosphate due to pathogenic variants in the FGF23, KLOTHO (KL), or GALNT3 genes." (PMID 38002303, 2023). "Age-related deterioration of renal function results in Klotho insufficiency, and hyperphosphatemia that contributes greatly to the aging phenotype." (PMID 35903083, 2022). "Similar to the original descriptions of klotho leading to premature senescence and hyperphosphatemia, patients with CKD suffer from a shorter life span, vascular calcifications, and bone disorders." (PMID 36246903, 2022). "A deficiency of either Klotho or FGF23 in mice results in excessive 1α-hydroxylase activity, overproduction of active vitamin D, and associated hyperphosphatemia and hypercalcemia." (PMID 35903083, 2022). "Hyperphosphatemia changes the amount of Klotho, FGF23, PTH, and calcitriol in the body, therefore increasing CVD incidence." (PMID 35928251, 2022). "So, in CKD patients, Klotho deficiency hampers FGF23 production, and the hyperphosphatemia resulting from it is one of the long-term consequences of CKD as well as vitamin D deficiency." (PMID 35812534, 2022).
hyperphosphatemia (continued). "Ablation of klotho in the proximal tubule of mice results in hyperphosphatemia upon challenge with a high phosphate diet only, consistent with a biologically relevant role of klotho in the proximal tubule." (PMID 36246903, 2022). "Klotho is an antiaging protein, and mice with genetic ablation of Klotho exhibit hyperphosphatemia and premature aging phenotypes, such as short life spans, vascular calcification, osteopenia, and skeletal muscle wasting." (PMID 34684606, 2021). "FGF23-null (FGF23−/−) mice were shown to develop hyperphosphatemia and high serum 1,25(OH)2D3, as well as premature aging features identical to Klotho-knockout (KL−/−) mice." (PMID 36188832, 2021). "This important insight provides a mechanism whereby Klotho, by preventing hyperphosphatemia, protects the vascular and renal systems, thereby prolonging lifespan." (PMID 33553988, 2021). "1,25(OH)2D/VDR–RXR acts in kidney to induce Klotho (a phosphaturic coreceptor for FGF23) to correct hyperphosphatemia, NPT2a/c to correct hypophosphatemia, and TRPV5 and CaBP28k to enhance calcium reabsorption." (PMID 33553988, 2021). "Old mice show hyperphosphatemia possibly because of an alteration of phosphate homeostasis with a decreased Klotho expression and the increment in the Na-Pi cotransporter in the kidney, as we described in previous studies." (PMID 34439556, 2021). "The phenotypic characteristics of genetic Klotho deficiency, such as bone disease, VC, CVD increased FGF23 levels, hyperphosphatemia, and premature mortality, resembles the uremic accelerated aging phenotype in man." (PMID 32982966, 2020). "A deletion of both PTH1R and Klotho from the kidney proximal tubule (PT-PTH1R/KL−/− mice) led to a severe disturbance of mineral metabolism including hyperphosphatemia at baseline and increased circulating phosphate in response to high phosphate diet." (PMID 32982979, 2020). "In contrast, other studies using an inducible promoter-Cre, Ndrg1-Cre, to delete Klotho from proximal tubules revealed a more pronounced effect on mineral metabolism with markedly elevated iFGF23 and hyperphosphatemia." (PMID 32982979, 2020). "Accordingly, the stable delivery of soluble Klotho has been reported to reduce chronic hyperphosphatemia and VC both in vitro and in vivo." (PMID 32982966, 2020). "FGF23 and Klotho mainly maintain urinary phosphorus excretion; any depleted activity of these molecules leads not only to hyperphosphatemia, but also to premature aging." (PMID 32438707, 2020). "In mice, for example, both fibroblast growth factor 23 (FGF23) and the renal transmembrane protein Klotho act as Pi-regulating hormones whose genetic ablation leads to hyperphosphatemia and premature aging phenotypes, including muscle atrophy." (PMID 33136552, 2020). "By using immunohistochemistry analysis, investigators showed that partial deletion of Klotho in distal tubule resulted in hyperphosphatemia with elevated plasma FGF23 and increased Npt2a protein expression in the proximal tubule apical membrane." (PMID 32982979, 2020). "α‐Klotho−/− (KLKO) mice exhibit hyperphosphatemia and markedly increased kidney Npt2c protein levels." (PMID 32026654, 2020). "Both Klotho and FGF23 deficient mice develop hyperphosphatemia and high serum levels of active 1,25-dihydroxyvitamin D levels together with premature aging features." (PMID 31546756, 2019). "Genetic deletion of Klotho in mice is characterized by a reduced lifespan, osteoporosis, arteriosclerosis, hyperphosphatemia, and ectopic calcification, hallmarks of CKD." (PMID 30713844, 2018). "The prevalence of high FGF23 levels (≥95th percentile) was 60% in CKD and 42% in CKD-T patients, despite a low prevalence of hyperphosphatemia and normal Klotho levels." (PMID 28795324, 2018). "A beneficial vascular role of Klotho has also been demonstrated in the context of hyperphosphatemia." (PMID 24695641, 2014).
hyperphosphatemia (continued). "Both Klotho knockout (Kl−/−) and Fgf23 knockout (Fgf23−/−) mice exhibit hypercalcemia, hyperphosphatemia with low to undetectable PTH levels, and severe osteomalacia." (PMID 22615584, 2012). "The observed hyperphosphataemia in Klotho and FGF23-mutant mice is due to hypervitaminosis D and increased expression/activity of renal sodium-dependent phosphate cotransporters." (PMID 22121479, 2012). "Disruption of Klotho (the obligatory co-receptor of FGF23) results in hyperphosphatemia with ectopic calcifications formed in blood vessels and kidneys." (PMID 22879941, 2012). "The phenotypes of Fgf23−/− and Klotho−/− (Kl−/−) mice are very similar and include hypercalcemia, hyperphosphatemia, hypervitaminosis D, suppressed PTH levels, and severe osteomalacia/osteoidosis." (PMID 22615584, 2012). "Mice that lack the klotho protein exhibit premature aging and develop hyperphosphatemia." (PMID 40535045, 2025). "Hyperphosphatemic familial tumoral calcinosis (HFTC) is a rare autosomal recessive disorder characterized by ectopic calcifications in periarticular soft tissues due to mutations in genes such as GALNT3, FGF23, or KL, leading to FGF23 deficiency or resistance and subsequent hyperphosphatemia." (PMID 40524990, 2025). "Hyperphosphatemia was linked with several key regulators of renal vascular calcification, such as elevated levels of fibroblast growth factor 23 (FGF23) and decreased expression of Klotho." (PMID 39497801, 2024). "Conversely, defects in klotho or FGF23 contribute to hyperphosphatemia." (PMID 37143722, 2023). "Second, soluble Klotho remedies hyperphosphatemia through interaction with FGFR1 in the kidney." (PMID 36338347, 2022). "However, the prevailing hyperphosphatemia in these mice was significantly reduced after Klotho treatment." (PMID 35813388, 2022). "Klotho deficient mice are completely resistant to FGF23 and thus develop hyperphosphatemia." (PMID 35928251, 2022). "Conversely, enhancing the levels of klotho by genetic ways or supplementation could rescue the hyperphosphatemia and severity of VC." (PMID 36402949, 2022). "Proteinuria may also act with hyperphosphatemia to increase the risk of ASCVD, which involve the NaPi-IIa, fibroblast growth factor 23, and klotho." (PMID 36369936, 2022). "Furthermore, according to the literature, imbalance in the FGF-23-Klotho pathway and its consequent hyperphosphatemia is connected to the progression of CKD." (PMID 35056905, 2021). "Phosphate load may lead to increased fibroblast growth factor 23, decreased vitamin D, increased intact parathyroid hormone, and decreased klotho; such a vicious cycle is likely activated even before hyperphosphatemia occurs." (PMID 33459122, 2021). "In addition to the oligo-anuric state, patients with advanced CKD/ESKD have a significant reduction in klotho and progressively lose the ability to prevent phosphate retention, resulting in hyperphosphatemia, vascular calcification, and cardiovascular disease." (PMID 32545510, 2020). "In addition, hyperphosphatemia is associated with VC in animal models of CKD, and mice with targeted deletion of FGF23 or klotho show hyperphosphatemia and VC." (PMID 29922171, 2018). "Since the FGF23 KO mice and the Klotho mice exhibited severe muscle wasting, we wondered whether hyperphosphatemia could directly affect the skeletal muscle cells, leading to sarcopenia." (PMID 30271655, 2018). "Recent studies have confirmed that the stable delivery of soluble klotho can reduce chronic hyperphosphataemia and VC in vitro and in vivo, and activating peroxisome proliferator-activated receptor γ enhanced the expression of klotho to inhibit Phosphate-induced VC in vascular SMCs." (PMID 30348110, 2018). "In a previous study, klotho knock-out mice had similarities with CKD patients, such as hyperphosphatemia, ectopic soft tissue calcification, and arteriosclerosis, suggesting that CKD might result from a state of klotho deficiency." (PMID 29506503, 2018).
hyperphosphatemia (continued). "Increasing plasma 1,25(OH)2D levels induced by decreased levels of renal Klotho may lead to further hyperphosphatemia because 1,25(OH)2D increases plasma Pi concentrations." (PMID 29371756, 2018). "Mice lacking Klotho or FGF23 exhibit a premature aging syndrome associated with abnormal mineral metabolism characterized by hyperphosphatemia, hypercalcemia, and hypervitaminosis D." (PMID 30271655, 2018). "This leads to a further compensatory increase in FGF-23 levels which fails to exert its phosphaturic and PTH-suppressing effects without Klotho, thereby enhancing hyperphosphatemia and overt hyperparathyroidism, conditions at high risk for CVD." (PMID 30200452, 2018). "Lack of Klotho is known to shorten life span and to cause organ atrophy, vascular calcifications, osteomalacia, hypercalcemia, hyperphosphatemia, elevated circulating vitamin D hormone, and increased peripheral insulin sensitivity in mice." (PMID 22319626, 2012). "Klotho-deficient mice are a genetic model of hyperphosphatemia without severe kidney injury." (PMID 39273260, 2024). "However, it is possible that pathologic changes are not directly caused by a loss of klotho or sKL, but indirectly by other pathologic changes that occur in the absence of klotho, such as hyperphosphatemia." (PMID 38791164, 2024). "In mice with normal kidney function, Klotho induction of autophagy by disruption of the formation of the Beclin1/Bcl2 complex, is one of the mechanisms critical for klotho prevention of premature aging and lifespan improvements that are unrelated to the attenuation of hyperphosphatemia." (PMID 34950686, 2021). "Consequently, Klotho knock-out mice display severe vascular disease, with widespread VC, endothelial dysfunction, and progressive atherosclerosis accompanied by hypervitaminosis D, hypercalcemia, and hyperphosphatemia." (PMID 32982966, 2020). "Furthermore, hyperphosphatemia induced by Klotho depletion in CKD is a trigger to renal osteopathy and vascular calcification, which may indirectly accelerate aging and increase mortality." (PMID 33362554, 2020). "However, injection of a mutated soluble Klotho isoform lacking the FGF receptor binding arm resulted in a striking downregulation of FGF23 target genes in the kidney with the development of hyperphosphatemia." (PMID 31546756, 2019). "Key drivers of CVD in CKD include hyperphosphatemia and elevated levels of fibroblast growth factor-23 (FGF23), and recent studies have highlighted the role of the Klotho protein in mitigating these risks." (PMID 41141519, 2025). "In patients with progressive CKD, phosphate retention, hyperphosphatemia, higher levels of FGF-23 and low expression of klotho are observed." (PMID 39113723, 2024). "Deletion of Klotho in mice results in a phenotype that resembles CKD, including hyperphosphatemia, elevated FGF23, ectopic soft tissue calcifications, and decreased plasma and renal Klotho." (PMID 35813388, 2022). "Klotho levels gradually decrease as CKD progresses and are inversely correlated with hyperphosphatemia." (PMID 35656113, 2022). "When GFR further decreases, decompensation of FGF‐23 occurs because of exacerbated phosphate excretory failure and decreased klotho protein, and patients with CKD develop hyperphosphatemia." (PMID 34418162, 2021). "Phosphate retention, progressive hyperphosphatemia, rising FGF23 levels and low Klotho expression are all observed in patients with progressive CKD and are associated with age-associated CVD." (PMID 32982966, 2020). "Hyperphosphatemia, hypercalcemia, hyperparathyroidism, and other factors induce vascular calcification, while matrix GLA protein, klotho, magnesium, and other factors inhibit progression of vascular calcification." (PMID 29614972, 2018). "The resulting reduction in klotho limits its regulation of FGF23 production and leaves hyperphosphataemia as the principal regulator of FGF23 secretion in CKD." (PMID 30348110, 2018).